BRCA2 (BRCA2 DNA repair associated)
Diseases named in the same sentence as BRCA2 in open-access papers (continued):
Sharing a sentence is not in itself a finding about the gene and the disease.
breast cancer (continued). "In summary, our study indicates that 2R/2R and 2R/1R were significantly associated with increased risk, and 1R/1R and 1R/0R were significantly associated with the decreased risk of BRCA1+ breast cancer, whereas 2R/1R was significantly associated with the increased risk of BRCA2+ breast cancer." (PMID 27148484, 2016). "The breast cancer susceptibility gene, BRCA2, is a major player involved in these functions." (PMID 27490902, 2016). "Thus, all published estimates of penetrance of PALB2 mutations are comparable to the breast cancer risk associated with BRCA2 mutations: 45 % (95 % CI, 31–56 %)." (PMID 27099641, 2016). "PALB2, a partner and localizer of BRCA2, is another gene commonly associated with breast cancer." (PMID 30460281, 2016). "Women carrying germline BRCA1 mutations have a cumulative risk at 70 years of 60% for breast cancer and 59% for ovarian cancer, whereas BRCA2 mutations appear to confer a similar risk of breast cancer in females (55%), but a lower risk (17%) for ovarian cancer." (PMID 27532258, 2016). "However, pathogenic mutations of BRCA1 and BRCA2 only explain 10–20% of breast cancers in patients with early-onset or a significant family history." (PMID 26824983, 2016). "Recently, the concept of “BRCAness” has been introduced to investigate sporadic breast cancers with defects in the HR-mediated DNA repair pathway, which endow them with critical features also observed in hereditary breast cancers carrying BRCA1 or BRCA2 germline mutation." (PMID 27788678, 2016). "We also showed that high-grade breast tumours were more likely to arise in male than in female BRCA2 mutation carriers, indicating that BRCA2 mutations might be associated with different breast cancer phenotypes in men and in women." (PMID 26857456, 2016). "In addition, we found two SNPs in TNFRSF11A significantly associated (P < 0.05) with breast cancer risk in BRCA2 mutation carriers." (PMID 27241552, 2016). "Targeting the defective repair with DNA double strand break-inducing agents like platinum compounds might be beneficial for BRCA1 or BRCA2 mutation carriers with breast cancer." (PMID 27323902, 2016). "Women carrying BRCA1 mutations are particularly at risk of developing breast cancer at very early age and ovarian cancer during their life, while women carrying a BRCA2 mutation tend to develop breast cancer later in their life and have a significantly lower susceptibility to ovarian cancer." (PMID 26852130, 2016). "However, it is worth noting that breast cancers in female BRCA2 mutation carriers frequently show a lobular morphology, thus suggesting differences in the pathogenic mechanisms of male and female BRCA2 breast cancer." (PMID 26857456, 2016). "Mutations in homology-directed repair genes like BRCA2 are linked to breast cancer susceptibility." (PMID 27779185, 2016). "All nine BRCA2 mutations were identified in women with breast cancer." (PMID 26843898, 2016). "BRCA1 and BRCA2 mutations account for 25–28% of hereditary breast cancers." (PMID 27899083, 2016). "According to some studies, BRCA2 mutations occur in 4-16% of male breast cancer patients." (PMID 27478808, 2016). "Germ-line mutations in BRCA1 and BRCA2 genes are associated with 5–10% of breast cancer incidence." (PMID 29138730, 2016). "Besides BRCA1 and BRCA2, inherited mutations in othertumor suppressor genes also increase the risk for breast cancer and other tumors." (PMID 27223485, 2016). "This particular BRCA2 mutation has been identified in families with familial breast cancer." (PMID 26846091, 2016). "The impact of mutations in either gene can be dramatic; 65 % and 45 % of women with deleterious mutations in BRCA1 or BRCA2, respectively, will develop breast cancer by age 70, and the risk increases to 85 % and 84 %, respectively, for women with a family history of breast cancer." (PMID 27716388, 2016).
breast cancer (continued). "Results might be pivotal for registration of olaparib as standard first line treatment in advanced BRCA1- or BRCA2-mutated breast cancer." (PMID 27323902, 2016). "Of the eight BRCA2 mutation-associated breast cancers with information on histopathology, hormone receptor status and HER2 status, five were ER/PR-positive, HER2-negative invasive ductal carcinomas and three were ER/PR-positive, HER2-positive invasive ductal carcinomas." (PMID 26843898, 2016). "Besides environmental triggers and hormones, inherited mutations in the breast cancer 1 (BRCA1) or BRCA2 genes markedly increase the risk for the development of breast cancer." (PMID 27241552, 2016). "Thus, we undertook a prospective analysis of plasma OPG levels and breast cancer risk in 206 women with a BRCA1 or BRCA2 mutation that were unaffected by breast cancer at the time of study enrollment." (PMID 27893411, 2016). "Notably, this was a frameshift BRCA2 variant truncating approximately 50% of the longest canonical transcript within a 29 year-old pancreatic cancer patient with a family history of breast cancer." (PMID 28003660, 2016). "Until now, only one study has identified a BRCA2 mutation in one patient with a carcinoma of the ampulla of Vater, but it was identified in an individual with a family history of breast cancer where this mutation had previously been identified in other family members." (PMID 27532258, 2016). "In the present study, we found that the frequency of BRCA1 and BRCA2 mutations was 23.3 % in our cohort of 133 Chinese women with familial breast/ovarian cancer, and the frequency of BRCA1 and BRCA2 mutations was 50 % in patients with a familial history of both breast cancer and ovarian cancer." (PMID 26852015, 2016). "Indeed, the risk of developing breast cancer in carriers of BRCA1 or BRCA2 mutation is about 45–80 %." (PMID 27129401, 2016). "The BRCA2 c.156_157insAlu mutation was observed with a frequency of 7.8% in male breast cancers, 3.0% in peritoneal/fallopian tube cancers, and 1.6% in pancreatic cancers, with estimated total contributions of germline BRCA2 mutations of 14.3%, 5.5%, and 2.8%, respectively." (PMID 27532258, 2016). "Despite the low number of patients in this study, it could be concluded that mutations in BRCA1 and BRCA2 occur in male breast cancer patients of luminal A subtype." (PMID 27478808, 2016). "Also, there were not enough HQ studies available to provide conclusive evidence using the best-evidence synthesis for an association between BRCA2 mutation carriership and unadjusted/adjusted metastasis-free survival of breast cancer patients." (PMID 25816289, 2015). "However, in patients with a suggestive personal and/or family history, a specific predisposing mutation in the breast cancer susceptibility gene-1 (BRCA1) or in the breast cancer susceptibility gene-2 (BRCA2) is identified in only fewer than 30% of cases." (PMID 26312763, 2015). "The breast cancer predisposition gene, BRCA2, has a large number of genetic variants of unknown effect." (PMID 26455428, 2015). "Patients with an established diagnosis of breast cancer found to have a BRCA1 or BRCA2 mutation also may experience feelings of worry." (PMID 26557407, 2015). "Furthermore, canine BRCA2 missense mutations, including some that affect BRCA2 function, were also reported in canine mammary tumors." (PMID 26202431, 2015). "In other words, alteration of RHAMM function in mammary epithelial differentiation may have a differential effect on breast cancer risk depending on whether it occurs in a BRCA1- or BRCA2-mutated background." (PMID 25830658, 2015). "CNVs have been reported to encompass genes known to be involved in breast cancer susceptibility, including BRCA1 and BRCA2, and therefore may similarly affect other genes involved in breast cancer-related pathways." (PMID 27600231, 2015).
breast cancer (continued). "A BRCA1 mutation was found in 18.4 % of women diagnosed with breast cancer at/or under the age of 40 compared to 11.2 % of women diagnosed at a later age; a BRCA2 mutation was found in 4 % of women diagnosed at/or under the age of 40 compared to 6.5 % of women diagnosed at a later age." (PMID 26183948, 2015). "While it remains unclear why canine BRCA2 expression levels are reduced in mammary tumor samples, this study found that the expression level of BRCA2 was associated with canine mammary tumorigenesis." (PMID 26202431, 2015). "Furthermore, in the latest large multiple center study, 1,583 patients with BRCA1 mutations and 881 with BRCA2 mutations, 383 (24%) and 454 (52%) of patients were administered tamoxifen, respectively, following the initial breast cancer diagnosis." (PMID 25435968, 2015). "To determine the reason why BRCA2 expression was decreased in canine mammary tumors, we performed a mutation analysis of the canine BRCA2 promoter region and splice variants, the transcript of which may lead to PTC and NMD." (PMID 26202431, 2015). "Furthermore, the life-time risk of breast cancer in male BRCA2 mutation carriers is approximately 8 – 10 times higher than the general population." (PMID 25632310, 2015). "We did detect two types of BRCA2 splice variants in 8 mammary tumor samples." (PMID 26202431, 2015). "However, BRCA1 and BRCA2 germline mutations are present in only half of all families with a strong family history of breast cancer." (PMID 25927356, 2015). "Later, a novel locus, encoding BRCA2, was discovered and linked to breast cancer susceptibility." (PMID 25869442, 2015). "Although we were careful not to recruit familial cases for our study it is interesting to note that in Uruguay there is a predominance of BRCA2 over BRCA1 mutations in breast cancer families, which may be linked to their ethnic origin." (PMID 25783644, 2015). "In this study, we investigated the antiproliferative effects and mechanism of PARP inhibitors ABT-888 (Veliparib), BSI-201 (Iniparib) and AZD228 (Olaparib) in breast cancer cell lines with BRCA1 or BRCA2 mutations and 9 different BRCA wild-type cell lines with BRCA1 allelic loss." (PMID 25975349, 2015). "Hence using the best-evidence synthesis there were not enough HQ studies available to provide conclusive evidence about the association between BRCA2 mutation carriership and recurrence-free survival of breast cancer patients." (PMID 25816289, 2015). "Our previous study has shown that male breast cancer mutations were BRCA2 mutations." (PMID 26489409, 2015). "This study and our results suggest that mitochondrial haplogroup T1a1 may modify the individual breast cancer risk in BRCA2 mutation carriers." (PMID 25925750, 2015). "Our review shows that, in contrast to currently held beliefs of many oncologists and despite 66 published studies, it is not yet possible to draw evidence-based conclusions about the association between BRCA1 and/or BRCA2 mutation carriership and breast cancer prognosis." (PMID 25816289, 2015). "The mutation frequency was higher in the subgroup of TNBC than in the premenopausal breast cancer patients: 23.3 % (7/30) of TNBC patients harbour a pathogenic mutation in either BRCA1 or BRCA2, compared to 12.0 % (11/92) of all premenopausal breast cancer patients." (PMID 26577449, 2015). "We specifically compared the genomic and gene expression profiles of CHEK2*1100delC breast cancers (n = 14) with BRCAX (familial non-BRCA1/BRCA2/CHEK2*1100delC mutated) breast cancers (n = 34) of the luminal intrinsic subtypes for which both SNP-array and gene expression data is available." (PMID 26553136, 2015). "BRCA2 mutations are in general less frequent than BRCA1 in younger white women with breast cancer." (PMID 26577449, 2015). "Interestingly, one study demonstrated that women with BRCA1 and BRCA2 mutations have greater susceptibility to breast cancer, but also higher fertility." (PMID 26056364, 2015).
breast cancer (continued). "Similarly, selective anti-proliferative effects of BRCA1 or BRCA2 (breast cancer, early onset)-deficient tumors have been demonstrated with olaparib." (PMID 26544897, 2015). "We next attempted to detect BRCA2 splice variants, which may contain frame-shift mutations, in mammary tumor samples using a modified method that we reported previously." (PMID 26202431, 2015). "A BRCA2 promoter sequence analysis of mammary tumors revealed nine promoter allele types." (PMID 26202431, 2015). "However, one of the detected 5’UTR polymorphisms, rs1801320, has been found to affect the splicing of RAD51 within the 5’UTR and to modify breast cancer risk among BRCA2 mutation carriers." (PMID 25918678, 2015). "Further research is needed to investigate whether let-7b might be able to distinguish BRCA2-associated from sporadic breast carcinomas." (PMID 26378051, 2015). "This mutation would be expected to produce the BRCA2 inherited breast cancer phenotype." (PMID 24963353, 2014). "As BRCA1 carriers are more likely to develop ER-negative disease, SNPs associated with this subtype will be more informative in models to predict overall breast cancer risk in these women, whereas SNPs associated with ER-positive disease will be more useful in BRCA2 carriers." (PMID 25919761, 2014). "Inherited mutations in BRCA1 or BRCA2 increase the risk of breast cancer in women by around 56–84%." (PMID 25293656, 2014). "For example, it is estimated that the penetrance of the breast cancer 2 (BRCA2) founder mutation in Iceland increased fourfold over the last century, and the cumulative incidence of sporadic breast cancer by age 70 also increased fourfold, from 2.5% to 11% of the population, over the same period." (PMID 25467785, 2014). "Higher circulating estradiol is associated in the general population with a pre-menopausal breast cancer risk, and BRCA2 carriers with breast cancer do have higher estradiol levels in the early follicular phase, but a similar association with circulating progesterone is not seen." (PMID 24478985, 2014). "Also, BRCA1 and BRCA2 genetic testing was performed to determine the association between gene mutations and the development of other tumors, including breast cancer." (PMID 24959251, 2014). "However, despite its association with inherited predisposition, somatic disease-causing mutations in BRCA1 or BRCA2 are extremely rare in sporadic breast cancer." (PMID 24591761, 2014). "Approximately 5% of all breast cancers can be attributed to a mutation in the BRCA1 or BRCA2 gene." (PMID 24742220, 2014). "Genetic mutations in BRCA1 and BRCA2 account for approximately 20% of breast cancer cases." (PMID 25360583, 2014). "A strong association was found between family history of breast cancer and a high frequency of Aldh1a1 expression in breast ductules in women, regardless of a hereditary breast-ovarian cancer syndrome status (Brca1 and Brca2 mutations), age, parity, or occurrence of cancer." (PMID 24594504, 2014). "Looking at the family histories of these cases, 4/8 families had a history of breast cancer, suggesting that like BRCA2, mono-allelic mutations in PALB2 may lead to the development of breast cancer." (PMID 24949998, 2014). "This mutation is expected to produce the BRCA2 inherited breast cancer phenotype." (PMID 24963353, 2014). "Analysis of the BRCA1 and BRCA2 genes in search of mutations in women diagnosed with breast cancer at an early age revealed both BRCA1 and BRCA2 mutations, suggesting that genetic testing for mutations in these genes should be offered to women with early onset breast cancer." (PMID 24678344, 2014). "In addition, the ER-specific associations in BRCA1 and BRCA2 carriers were mainly in the same direction and of a magnitude similar to the associations observed with breast cancer stratified by ER expression status in the general population." (PMID 25919761, 2014).
breast cancer (continued). "Further studies are needed to investigate whether FANCD2-related breast cancers are similar to those seen BRCA2 mutation carriers." (PMID 25093046, 2014). "Furthermore, the presence of genomic structural rearrangement resulting in CNVs in other genes that predispose breast cancer in conjunction with BRCA2 point mutations demonstrated a highly complex genetic etiology in Brazilian breast cancer families." (PMID 24884479, 2014). "Additionally inherited mutations of BRCA1 and BRCA2 (breast cancer 1/2) are associated with patients who have hereditary breast cancer, accounting for 5–10% of all breast cancer patients." (PMID 25207935, 2014). "Considering the proven existence of an inversely correlation between breastfeeding duration and breast cancer risk, an important case-control study, examined the relationship between breast-feeding and breast cancer risk among women who carried deleterious mutations in the BRCA1 or BRCA2 gene." (PMID 24763114, 2014). "BRCA1 and BRCA2 are the two major breast cancer susceptibility genes." (PMID 24728327, 2014). "However, it’s widely accepted that hereditary transmission of some predisposition genes, especially BRCA1 and BRCA2, are the most known factors to be directly involved in the pathogenesis of breast cancer and is associated with 5–10% of breast cancer cases." (PMID 25926863, 2014). "In addition, carrying BRCA1/BRCA2 germline mutations has been associated with a high risk of contralateral breast cancer." (PMID 24834114, 2014). "Despite the fact that women who inherited mutations in the BRCA1 and BRCA2 genes have a high risk of developing breast cancer, studies have also shown that significant exposure to certain metal compounds and organic solvents also increases the risks of mammary gland carcinogenesis." (PMID 23762568, 2013). "To identify common genetic variants that modify the breast cancer risk associated with BRCA2 mutations, we have built upon our previous work in which we examined genetic variants across the genome in relation to breast cancer risk among BRCA2 mutation carriers." (PMID 23544012, 2013). "Furthermore, BRCA-1 and BRCA-2 germ line mutations account for only a quarter of the total breast cancer cases and a significant portion of women with breast cancer acquire the affliction in the absence of this familial link." (PMID 29147364, 2013). "Knowledge of the 6p24 locus might provide further insights into the biology of breast cancer development in BRCA2 mutation carriers." (PMID 23544012, 2013). "Genomic abnormalities resulting in loss of DNA repair function are associated with the development of several tumours, i.e. loss of BRCA1 or BRCA2 genes in hereditary ovarian or breast cancer, or defects in the DNA mismatch repair pathway in hereditary non-polyposis colorectal cancer." (PMID 24244370, 2013). "This panel may have clinical utility for women with BRCA2 mutations weighing options for medical prevention of breast cancer." (PMID 23544012, 2013). "Therefore, new methods are needed to aid in the interpretation of uncertain variants as well as to increase the detection rate of BRCA1 and BRCA2 germline mutations for genetic counseling and clinical management of familial breast cancers." (PMID 23704984, 2013). "However BRCA1 and BRCA2 have been associated with mammary tumours in English springer spaniels in Sweden." (PMID 23738139, 2013). "We replicated previously reported breast cancer susceptibility alleles in these BRCA2 mutation carriers and for several regions (including FGFR2, MAP3K1, CDKN2A/B, and PTHLH) identified SNPs that have stronger evidence of association than those previously published." (PMID 23544012, 2013). "This may be of particular significance to breast cancer therapy, as a significant percentage of hereditary breast cancers carry the BRCA1 or BRCA2 mutations and thus are deficient in HR." (PMID 24137461, 2013).